INS (insulin)
Diseases named in the same sentence as INS in open-access papers (continued):
Sharing a sentence is not in itself a finding about the gene and the disease.
Insulin resistance (continued). "Pre-treatment with TNFα induced insulin resistance, indicated by reduced AKT S473 phosphorylation in response to insulin." (PMID 29661693, 2018). "When applying BAKE to an experimental animal model of insulin resistance progression, we discovered a novel regulatory transcription factor KLF4 to interact with IRS2 and TSC2, two key intermediates in the insulin signaling pathway." (PMID 30240435, 2018). "Mean QUICKI and HOMA-IR of the 36 subjects indicated that they, as a whole, had decreased insulin sensitivity (QUICKI index < 0.357) and insulin resistance (HOMA-IR > 2.5)." (PMID 29498693, 2018). "The change of HOMA2 %B, an index reflects the ability of insulin secretion was negatively corresponded to the glucose levels, and the trends of HOMA2 IR, an index shows insulin resistance, were positively correlated to the glucose levels." (PMID 29338697, 2018). "We measured fasting serum insulin and glucose, conducted a homeostatic model assessment of insulin resistance(HOMA-IR), and calculated the quantitative insulin sensitivity check index(QUICKI)." (PMID 30470212, 2018). "Previously study showed that yoga intervention reduced insulin level and HOMA-derived insulin resistance index in healthy subjects compared to their pre-intervention baseline values." (PMID 30294284, 2018). "Skeletal muscle is of major importance in insulin resistance and T2DM as it accounts for 85% of whole body insulin-dependent glucose uptake and therefore plays a critical role in maintaining systemic glucose metabolism." (PMID 29373583, 2018). "Diacylglycerol accumulation promotes insulin resistance by activating the PKCΘ and ε impairing IRS tyrosine phosphorylation and therefore downstream insulin signaling." (PMID 30116154, 2018). "As a result, T+leucine treatment impaired mitochondrial function, reduced insulin-stimulated GLUT4 translocation and glucose uptake, and induced insulin resistance." (PMID 29552281, 2018). "In this context, oxidative stress induces insulin resistance in adipocytes and muscle cells via interaction with PI3-kinase and Akt signaling, decreases insulin secretion by β cells, alters cellular glucose uptake and lipogenesis." (PMID 30360467, 2018). "Insulin resistance was evaluated by HOMA-IR and insulin secretion was evaluated by HOMA-β, Stumvoll first phase and second phase indexes." (PMID 30505337, 2018). "Serum levels of insulin, Apelin, glucose, tumor necrosis factor-α(TNF-α), interleukin-1β (IL-1β) and the homeostasis model assessment of insulin resistance (HOMA-IR) were alsomeasured using commercial kits." (PMID 29845798, 2018). "We propose that increased insulin secretion led to increased levels of circulating insulin in β-CB1R−/− mice, eventually resulting in insulin resistance." (PMID 29497784, 2018). "This lowest dose of JPP improved insulin signalling as indicated by the increased insulin sensitivity (QUICKI) and decreased insulin resistance (FIRI)." (PMID 30186630, 2018). "BIGTT-AIR: index for acute insulin response, BMI: body mass index, HOMA-B: HOMA for beta cell function, HOMA-IR: HOMA for insulin resistance." (PMID 30514227, 2018). "Considering Tie2‐CYP2J2‐Tr‐HF mice had a reduction in body weight gain and insulin levels, the potential effects of endothelium‐specific CYP2J2 overexpression on aging‐related adiposity and insulin resistance were explored in this study." (PMID 29318723, 2018). "The group of women with previous GDM showed signs of insulin resistance featured by increased plasma insulin levels during the OGTT and decreased Matsuda index of insulin sensitivity and a relatively reduced insulin secretion by a decreased disposition index." (PMID 29764499, 2018). "Insulin sensitivity was improved as indicated by oral glucose tolerance test (OGTT), insulin tolerance test (ITT) and homeostasis model assessment of insulin resistance (HOMA-IR)." (PMID 30374328, 2018).
Insulin resistance (continued). "Adiponectin which generally negatively correlates with the body fat, fasting insulin, and oral glucose tolerance were increased in our HFHF model as observed in obese patients with liver dysfunction and insulin resistance." (PMID 30363947, 2018). "The observations from animal studies above spurred us to examine the fasting blood glucose (FBG), fasting insulin (FINS), insulin resistance index (HOMA-IR) and liver index (LI) in NAFLD development." (PMID 29324774, 2018). "Compared with subjects with eGFR < -1 SD, patients with eGFR > 1 SD showed higher SBP, AST, ALT, glucose and insulin during OGTT, insulin resistance; they also had lower sensitivity indexes after both crude analysis and ANCOVA." (PMID 29505614, 2018). "We next used radiolabeled glucose tracer and whole‐body imaging after insulin injection in 6‐week HFD‐fed WT and Msr1−/− mice in order to determine tissue‐specific insulin resistance." (PMID 30485705, 2018). "As insulin resistance increases, the fasting insulin levels are inversely related to BMD, and this relationship becomes more significant as the degree of insulin resistance increases." (PMID 30185190, 2018). "Insulin resistance was also observed in AQP7 KO mice as they aged, with increased fasting plasma glucose and insulin concentrations." (PMID 29914059, 2018). "On the other hand, HbA1c, fasting plasma glucose (FPG), fasting immunoreactive insulin (FIRI) levels, and homeostasis model assessment for insulin resistance (HOMA-IR) were similar in the two groups." (PMID 29614124, 2018). "Fasting plasma insulin (FPI) and insulin tolerance test (ITT) were measured to characterize insulin secretion in response to the glucose challenge and insulin resistance." (PMID 29755549, 2018). "Hepatic SHBG output is suppressed by insulin, and therefore, decreased circulating SHBG is a surrogate marker of hyperinsulinemia in the setting of systemic insulin resistance." (PMID 29590099, 2018). "Reported amelioration of insulin resistance by the constituent herbs lends support to the HAEF mediated 2-DG uptake in the presence of insulin." (PMID 29606113, 2018). "Insulin resistance in in vitro models was defined by impaired HA-GLUT4 translocation to the plasma membrane and insulin-mediated 2-deoxyglucose (2DOG) uptake." (PMID 29402381, 2018). "Due to the structural similarity of insulin, proinsulin, insulin-like growth factor-I (IGF-I) and IGF-II and resemblances of the insulin and IGF-I receptor, IGF-I was proposed as another treatment option for patients with severe insulin resistance." (PMID 29695048, 2018). "This popular tool is used to assess beta-cell function (HOMA β-cell) or insulin resistance (HOMA-IR) by measuring the plasma fasting glucose and baseline insulin concentrations." (PMID 30151373, 2018). "Transmission of insulin signaling is aberrant in HFD-fed mice, especially in the muscle, supporting the development of insulin resistance, although the severity of the resistance is lower than is found in KK-Ay mice." (PMID 29768504, 2018). "Insulin resistance, quantified by the steady-state plasma glucose (SSPG) test, in which a higher value indicates relative resistance to insulin-mediated glucose uptake, ranged from 45 mg/dL to 335 mg/dL, reflecting great heterogeneity in the cohort." (PMID 30040822, 2018). "The homeostasis model assessment of insulin resistance (HOMA-IR, fasting blood glucose [mg/dL] × fasting insulin [μU/mL] /405) was 0.9 versus 16 in NC-fed mice versus G+HFHSD-fed mice at 30 weeks of age." (PMID 29364977, 2018). "A 15-month-old GK rat (D) exhibited a characteristic feature typical of type 2 diabetes, and it includes moderate hyperglycemia, impaired glucose tolerance, and insulin resistance, HOMA-IR, assessed based on fasting plasma glucose and insulin levels." (PMID 30510624, 2018).
Insulin resistance (continued). "It has been shown that ER stress drastically contributes to hepatic insulin resistance by inducing inflammatory responses involving NF-κB and JNK signaling, which further affect insulin signaling." (PMID 30692925, 2018). "For example, elevated O-GlcNAcylation act as an intermediate in the insulin signal pathway, reducing the insulin-stimulated phosphorylation of Akt2 and IRS-1, thereby subsequently leading to insulin resistance in rat primary adipocytes." (PMID 30082668, 2018). "Of these, 451 participants took an oral glucose tolerance test to assess homeostatic model assessment of insulin resistance (HOMA-IR) and Matsuda insulin sensitivity index (ISI)." (PMID 30426019, 2018). "Our previous studies revealed that old Ghsr−/− mice have improved insulin sensitivity, and other studies showed that GHS-R ablation attenuated diet-induced insulin resistance." (PMID 30275401, 2018). "With regard to insulin resistance, several studies have reported that an acute ECC exercise increases glycemia, insulin levels, and homeostasis model assessment of insulin resistance." (PMID 30131705, 2018). "Considering that insulin resistance in adipocytes primarily arises from depletion of Glut4, up-regulation of Glut4 by APS contributed to improving insulin sensitivity in the 3T3-L1 adipocytes." (PMID 30347867, 2018). "Therefore, cardiovascular diseases may be a consequence of insulin resistance rather than being caused by toxic effects of high insulin or glucose concentrations." (PMID 29732028, 2018). "Inhibition of LOX activity in transgenic HIF-1α mice resulted in an improvement in the insulin sensitivity which highlights the critical role of LOX in HIF-1α mediated fibrosis and insulin resistance." (PMID 30622603, 2018). "In our model, we observed that treatment with high palmitate concentrations (0.5 mM for 24 h) inhibited insulin–stimulated GLP-1 secretion and induced a state of insulin resistance at the level of the IRS-1/AKT pathway." (PMID 30487448, 2018). "Insulin sensitivity was assessed by 1/homeostasis model assessment of insulin resistance (1/HOMA-IR) and Matsuda insulin sensitivity index (ISIM); β-cell function was assessed by disposition index (DI)." (PMID 29707577, 2018). "Insulin administration was recommended for 10 patients (low insulin after OGTT and low fasting C-peptide), metformin for 4 (insulin resistance feature) and diet control in 5 of them since pre-concepcional period." (PMID 30346951, 2018). "Regarding insulin resistance, the current study demonstrated that in HCV patient group fasting blood glucose level, fasting insulin level and HOMA- IR were significantly higher than the control group (data not presented)." (PMID 30366460, 2018). "Accumulating studies indicate that chronic inflammation is considered an important driver of insulin resistance and type 2 diabetics, and IKK-NF-κB is one of the principal inflammatory pathways that disrupt insulin action." (PMID 30210342, 2018). "Reduced insulin-induced activation of the signaling pathway and GLUT4 translocation lead to the development of insulin resistance and T2DM." (PMID 30249008, 2018). "Glucose and insulin tolerance testing (GTT and ITT, respectively) were then performed to assess glucose disposal and insulin resistance, respectively, both of which are hallmarks of T2D." (PMID 30446513, 2018). "On the other hand, impaired insulin signaling in the MΦs of PDK1KO mice aggravated inflammation and insulin resistance." (PMID 30451856, 2018). "Fasting blood glucose and plasma insulin levels were significantly lower in Blnc1 LKO mice, suggesting that liver-specific inactivation of Blnc1 protects mice from HFD-induced insulin resistance." (PMID 30061575, 2018). "Relatively lower expression of PLIN2 can promote the reduction of hepatic fibrosis and enhance insulin sensitivity, while simultaneously suppressing PLIN2 and PLIN3 can lead to insulin resistance." (PMID 29678171, 2018).
Insulin resistance (continued). "PLIN5 plays an important role in triacylglycerol metabolism and insulin action in skeletal muscle, and PLIN5-null mice developed skeletal muscle insulin resistance." (PMID 29409445, 2018). "However, the role of POPs may be more salient in beta-cell dysfunction-dominant T2D than insulin resistance-dominant T2D because the overproduction of insulin by pancreatic beta-cells during insulin resistance can mask the direct effect of POPs on beta-cell function." (PMID 30542326, 2018). "When insulin resistance occurs, elevated FFA levels acutely increase beta-cell mass and insulin secretion to compensate for insulin insensitivity." (PMID 30061862, 2018). "Pioglitazone, an insulin sensitizer, is administered to PCOS patients with insulin resistance to induce ovulation but the mechanisms by which this occurs have not been elucidated." (PMID 29580285, 2018). "Together, our results indicated that 5-PAHSA can significantly reduce high insulin- and TNF-α-induced insulin resistance in HepG2 cells and 3T3-L1 cells." (PMID 30666198, 2018). "Fasting plasma glucose and insulin levels were very variable in the T2DM group, which resulted in a highly variable HOMA‐IR score, reflecting different degrees of insulin resistance in the nine T2DM rats." (PMID 30040147, 2018). "As calculated from serum glucose and insulin levels at fasting state, HOMA-IR, an index of insulin resistance, was higher in the control group than in the normal-control." (PMID 30041479, 2018). "Insulin resistance is thought to be critical to the development of NAFLD, and insulin downregulates autophagy in response to nutrient supplies, but autophagy modulates insulin sensitivity as well." (PMID 30249977, 2018). "Previous study reported that adipocyte Metrnl controls insulin sensitivity through the peroxisome proliferator-activated receptor gamma (PPARγ) pathway and suggested that adipocyte Metrnl is an inherent insulin sensitizer and may be a therapeutic target for insulin resistance." (PMID 29854769, 2018). "VATCSA, measured by single-slice CT scan, has shown to be positively correlated with homeostasis model assessment of insulin resistance (HOMA-IR) and fasting insulin concentrations in persons with SCI." (PMID 30169541, 2018). "In addition, women with a greater early-pregnancy BMI were more likely to be prescribed metformin therapy, which we speculate may be due to the beneficial effects of metformin on insulin resistance or the desire to avoid weight gain that may be incurred with insulin treatment." (PMID 29522471, 2018). "Insulin resistance was estimated by calculating the homeostatic model assessment for insulin resistance (HOMA-IR) index, and the fasting insulin (FINS, pmol/L) × fasting glucose (mg/dL)/(22.5 × 6.965) levels were measured." (PMID 29849623, 2018). "Our results build on this previous work by showing that MSR1 provides a unique protection from excessive insulin resistance compared to other Class A scavenger receptors, since MARCO was dispensable for changes in insulin sensitivity in obese mice." (PMID 30485705, 2018). "Oxidative stress in insulin resistance generates FFA and AGE products which result in glucotoxicity and impairment of insulin signaling." (PMID 29950970, 2018). "Adipose tissue inflammation occurs prior to hepatic tissue inflammation in insulin-resistant, obese C57BL/6 mice, likely indicating that it contributes to the development of insulin resistance, with similar results being reported in CD-1 mice." (PMID 30249283, 2018).
Insulin resistance (continued). "Plasma insulin levels, HOMA-IR, office systolic and diastolic blood pressure, total cholesterol, triglyceride, LDL-C, HDL-C, and presence of insulin resistance were statistically different between groups." (PMID 30092787, 2018). "Early diagnosis of NAFLD in obese children is important for possible prediction of further metabolic disorders, which was supported in our study through significantly higher insulin concentration and HOMA-IR values related to insulin resistance." (PMID 29854715, 2018). "Simultaneously, homeostasis model assessment of insulin resistance (HOMA-IR) calculated as FBG and serum insulin in T2DM rats significantly increased, compared to control rats." (PMID 30135489, 2018). "Thus, it is possible that upregulation of IL-6 may not be causative in HFD-induced insulin resistance but persistent decreases in IL-6 may be sufficient to improve insulin sensitivity in mice fed HFD." (PMID 29562620, 2018). "Of the various molecular mechanisms thought to be involved in development of insulin resistance, we chose to include the effects of FFA, ROS mediated inhibition of insulin signaling, and degradation of mitochondrial function." (PMID 29444133, 2018). "Increased insulin resistance impairs energy, glucose and lipid metabolism; and leads to the development of obesity, T2DM and dyslipidemia and it eventually impairs brain insulin sensitivity, which also contributes to AD." (PMID 30380669, 2018). "As the relationship between obesity and insulin resistance is well known, our subjects with the highest BMI percentile had the highest average HOMA-IR as well as plasma concentrations of insulin in adolescents of this study including intervention program." (PMID 29391561, 2018). "In a Drosophila model of insulin resistance, treatment with MSDC-0160 significantly enhanced insulin sensitivity." (PMID 29793507, 2018). "Insulin resistance is a major pathophysiology of sarcopenia and NAFLD because both liver and muscle are target organs for insulin." (PMID 30274215, 2018). "Fasting serum insulin concentration and HOMA-IR were higher in TRIM31−/− mice, indicating insulin resistance in TRIM31−/− mice (P < 0.05)." (PMID 29497383, 2018). "Nonetheless, arterial stiffness can develop in younger individuals in the setting of insulin resistance, obesity and T2DM and evidence indicates that obese, insulin resistant and diabetic women are more prone to develop vascular stiffness than men." (PMID 29669555, 2018). "An 8-week Hatha yoga intervention was shown to reduce insulin level and HOMA-derived insulin resistance index in healthy subjects compared to their pre-intervention baseline values." (PMID 30294284, 2018). "As intact insulin signalling in the ARC is essential for maintaining energy homeostasis, ARC insulin resistance also likely contributes strongly to the peripheral insulin resistance observed in the hyperinsulinaemic–euglycaemic clamps in recuperated offspring." (PMID 30043179, 2018). "Current studies were focusing on the role of insulin secretion and action in the pathophysiology of PCOS, which was assumed to have a strong correlation with insulin resistance." (PMID 30775682, 2018). "Homeostatic model assessment for insulin resistance index (HOMA-IR) is calculated by fasting glucose and insulin levels, and it was highly elevated in response to HFD feeding, up to 3.9-fold when compared to the control group." (PMID 29783731, 2018). "The level of insulin resistance was also higher in the TBI/HSCT group (p = 0.04), while fasting blood glucose and insulin levels also tended to be higher in that group (p = 0.1 and p = 0.07 respectively)." (PMID 30400990, 2018). "Previous animal studies revealed that expression of GGPPS expression was found to be higher in insulin-resistant adipose tissues, which activate MAPK/Erk1/2 pathway through Ras-prenylation leads to insulin resistance." (PMID 34466413, 2018).